BST2 (bone marrow stromal cell antigen 2)
Description:
IFN-induced antiviral host restriction factor which efficiently blocks the release of diverse mammalian enveloped viruses by directly tethering nascent virions to the membranes of infected cells. Acts as a direct physical tether, holding virions to the cell membrane and linking virions to each other. The tethered virions can be internalized by endocytosis and subsequently degraded or they can remain on the cell surface. In either case, their spread as cell-free virions is restricted. Its target viruses belong to diverse families, including retroviridae: human immunodeficiency virus type 1 (HIV-1), human immunodeficiency virus type 2 (HIV-2), simian immunodeficiency viruses (SIVs), equine infectious anemia virus (EIAV), feline immunodeficiency virus (FIV), prototype foamy virus (PFV), Mason-Pfizer monkey virus (MPMV), human T-cell leukemia virus type 1 (HTLV-1), Rous sarcoma virus (RSV) and murine leukemia virus (MLV), flavivirideae: hepatitis C virus (HCV), filoviridae: ebola virus (EBOV) and marburg virus (MARV), arenaviridae: lassa virus (LASV) and machupo virus (MACV), herpesviridae: kaposis sarcoma-associated herpesvirus (KSHV), rhabdoviridae: vesicular stomatitis virus (VSV), orthomyxoviridae: influenza A virus, paramyxoviridae: nipah virus, and coronaviridae: SARS-CoV. Can inhibit cell surface proteolytic activity of MMP14 causing decreased activation of MMP15 which results in inhibition of cell growth and migration. Can stimulate signaling by LILRA4/ILT7 and consequently provide negative feedback to the production of IFN by plasmacytoid dendritic cells in response to viral infection. Plays a role in the organization of the subapical actin cytoskeleton in polarized epithelial cells. Isoform 1 and isoform 2 are both effective viral restriction factors but have differing antiviral and signaling activities. Isoform 2 is resistant to HIV-1 Vpu-mediated degradation and restricts HIV-1 viral budding in the presence of Vpu. Isoform 1 acts as an activator of NF-kappa-B and this activity is inhibited by isoform 2.
Synonyms: BST-2; CD317; tetherin; HM1.24
Tractability: Small molecule: a structure with a bound ligand is known; it has a binding pocket of medium quality. Antibody: UniProt places it where antibodies can reach, with high confidence; its Gene Ontology location is reachable by antibodies, with high confidence; UniProt predicts a signal peptide or a membrane-spanning region. PROTAC: UniProt records ubiquitination sites on it; ubiquitination databases record sites on it; its protein half-life has been measured.
Gene: Protein-coding gene on chromosome 19 (17,402,933 to 17,405,665, reverse strand). Ensembl gene ENSG00000130303.
Subcellular location: Golgi apparatus, trans-Golgi network; Cell membrane; Membrane raft; Cytoplasm; Apical cell membrane; Late endosome
Subcellular location (Human Protein Atlas): Golgi apparatus; Vesicles
Pathways (Reactome):
Immune System: Interferon alpha/beta signaling; Neutrophil degranulation
Disease: SARS-CoV-1 activates/modulates innate immune responses
Gene Ontology:
Molecular function: identical protein binding; metalloendopeptidase inhibitor activity; protein binding; protein homodimerization activity; RNA binding
Biological process: defense response to virus; innate immune response; negative regulation of cell growth; negative regulation of cell migration; negative regulation of intracellular transport of viral material; negative regulation of plasmacytoid dendritic cell cytokine production; negative regulation of viral genome replication; positive regulation of canonical NF-kappaB signal transduction; response to virus; positive regulation of leukocyte proliferation; regulation of actin cytoskeleton organization; response to interferon-alpha; response to interferon-beta; response to type II interferon
Cellular component: cell surface; cytoplasm; extracellular exosome; Golgi apparatus; late endosome; membrane; multivesicular body; plasma membrane; apical plasma membrane; azurophil granule membrane; membrane raft
Genetic constraint (gnomAD): Loss-of-function variants: 10 observed, 17.5 expected, observed/expected ratio (o/e) 0.57, 90% interval 0.35 to 0.97. The synonymous counts are far from expectation, so gnomAD's model fits this gene poorly and the ratio says little. Missense variants: 183 observed, 232.85 expected, observed/expected ratio (o/e) 0.79, 90% interval 0.7 to 0.89. Synonymous variants: 75 observed, 101.41 expected, observed/expected ratio (o/e) 0.74, 90% interval 0.61 to 0.9.
Homologues: Orthologues: chimpanzee BST2 (97% identical), macaque BST2 (77% identical), pig BST2 (43% identical), dog BST2 (41% identical), mouse Bst2 (35% identical), rat Bst2 (31% identical).
Diseases named in the same sentence as BST2 in open-access papers:
BST2 is named in the same sentence as 135 diseases in open-access papers, as found by Europe PMC text mining. Sharing a sentence is not in itself a finding about the gene and the disease. The quoted sentences say what the papers report.
viral infection (59 papers, 2011 to 2025). "Studies of BST2-deficient mice imply a complex role in the regulation of viral infection; it also functions as an endogenous ligand for LILRA4, also known as ILT7, and inhibits cytokine production, although its precise biological roles remains contentious." (PMID 27359105, 2016). "Nevertheless, studies in BST2-deficient mice imply a more complex role for this protein in regulating viral infection." (PMID 24594933, 2014). "In viral infection cycles, many host membrane-associated antiviral factors could block their replication, such as bone marrow stromal antigen 2 (BST-2), serine incorporator 5 (SERINC5, SER5), membrane-associated RING-CH protein 8 (MARCH8), and interferon-induced transmembrane protein 3 (2, –, 5)." (PMID 39868869, 2025). "Upregulation of the Stat1-mediated response to the virus, interferon response, immune system activation, and ISGs, such as Rsad2, IFITM3, Cxcl9, Bst2, and Oas2, across all strains confirmed ongoing viral infection." (PMID 39875898, 2025). "Upregulation of the Stat1-mediated response to the virus, interferon response, immune system activation, and interferon-stimulated genes (ISGs; e.g., Rsad2, IFITM3, Cxcl9, Bst2, and Oas2) across all strains confirmed ongoing viral infection." (PMID 39875898, 2025). "Apart from its role in inhibiting viral release, BST2 also functions as an innate immune sensor during viral infections, activating NF-κB through interaction with ILT7/LILRA4 to induce inflammatory responses." (PMID 39840076, 2024). "One of the primary ways that BST2 can combat viral infections is by tethering viral particles to the cell surface." (PMID 37922253, 2023). "BST2 is an interferon-induced type-II membrane protein and a major host restriction factor that plays an important role in the innate immune response to viral infections." (PMID 35163504, 2022). "The STRING database revealed that three possible target proteins interacted with SLFN, including BST2, SAMHD1, and TRIM5, previously implicated in viral infection." (PMID 36090985, 2022). "BST2 has also been reported to have a pro-inflammatory function through the Syk/TRAF2/TRAF6/TAK1/NF-κB pathway under conditions of viral infection." (PMID 35316682, 2022). "BST2+ macrophages have been reported to play an important role in restricting viral infection, which indicates an active innate immune status." (PMID 35316682, 2022). "Many factors have been implicated in the up-regulation of BST2 expression, notably IFN-α, IFN-γ, and even viral infections." (PMID 35865015, 2022). "After viral infection, E3 ubiquitin ligase MARCH8 is recruited by antiviral factor Tetherin (BST2/CD317) and mediates K27-linked ubiquitination of MAVS at K7." (PMID 34566944, 2021). "Bone marrow stromal cell antigen 2 (BST2) is well-known as a natural immune factor in viral infections and is highly expressed in a majority of tumors." (PMID 33436584, 2021). "BST-2 is an interferon-inducible factor that tethers various nascent enveloped viruses on the cell surface, playing an important role in viral infection." (PMID 34305826, 2021). "Marked upregulation of Oasl2 and Bst2 proteins, both of which are involved in interferon signalling, particularly in response to viral infections, was a major finding." (PMID 31683630, 2019). "BST2 is an antiviral antigen expressed by different immune cell types that plays complex roles in the regulation of viral infection." (PMID 30409222, 2018). "Through this ability to tether and signal, BST‐2 regulates host response to viral infection either by inhibiting release of nascent viral particles or in some models inhibiting viral dissemination." (PMID 27042298, 2016). "IFNs play important roles in host defense against viral infection by inducing the expression of a diverse range of antiviral factors, including BST‐2." (PMID 27042298, 2016).
viral infection (continued). "We start by discussing the role of BST‐2 in viral infections and evolutionary adaptation of viruses to BST‐2, to the new discoveries about the involvement of BST‐2 in disease manifestation." (PMID 27042298, 2016). "The ability of BST-2 to restrict viral infection relies on its expression by cell types permissive to infection." (PMID 26566124, 2015). "As an important arm of innate immunity against viral infection, BST-2/tetherin is a host factor capable of restricting the release of virions." (PMID 26431433, 2015). "Numerous studies have addressed the ability of BST-2 to restrict release of different viruses in vitro, however less is known regarding its ability to modulate viral infections in vivo." (PMID 26566124, 2015). "While its expression is induced by interferon (IFN) in the event of initial viral infection, BST2 itself negatively regulates IFN to minimize undesirable effects of prolonged IFN exposure, such as autoimmune diseases." (PMID 23840623, 2013). "Taken together these data demonstrate that BST2 expression increased viral infection of fibroblasts and that this increase of infection was responsible for increased virus production of these cells." (PMID 22072961, 2011). "BST2 and C3 play a role in the immune response and acts as a restriction factor against viral infections, reduced expression of which may indicate a compromised immune defense in sun-exposed skin, making it more susceptible to infections and inflammation." (PMID 39540047, 2024). "Studies of BST2 are based on functionality and blocking the release of viruses that can infect humans and other species; however, little information exists regarding viral infections in bovines." (PMID 37111415, 2023). "A deeper understanding of BST2-mediated promoter regulation may inform the design of innovative therapeutic approaches against exogenous viral infections and endogenous conditions like autoimmune diseases and cancer." (PMID 36176574, 2022). "The high expression of several interferon-induced viral-response genes (e.g. Bst2, Ifitm3, Ube2l6, and Rnf213) in the control ‘interferon’ cluster might point to a state of general surveillance for viral infection at baseline." (PMID 34939923, 2021). "In addition, it remains to be determined what effect BST2-specific inhibition of morbillivirus H proteins has on viral infection in vivo." (PMID 31366072, 2019). "Indeed, since IRFs are induced following TLR activation by viral infections, the upregulation of BST-2 expression in virus-infected cells in response to virus-induced IRF-7 activation would ensure that host cells maintain BST-2-mediated virus restriction." (PMID 31426525, 2019). "Based on the inhibitory effect of BST2 on virion secretion, BISPR may be involved in regulating viral infection partially by increasing the expression of antiviral protein BST2." (PMID 30072977, 2018). "We next examined whether the modest effect of BST-2 on LCMV multiplication in cultured cells had any implications in the establishment of a persistent viral infection in vivo." (PMID 30028868, 2018). "Emerging experimental and clinical evidence on the various functions of BST‐2 and the progress in our understanding of the involvement of innate immune responses to viral infections, inflammation, and cancer has prompted the need for a discussion on the role of BST‐2 in the host." (PMID 27042298, 2016). "Whether BST‐2 induces autophagy in immune cells that are relevant to most virus infection is yet to be determined." (PMID 27042298, 2016). "In addition to viral tethering, BST-2 can exert other immunomodulatory functions during viral infection." (PMID 26566124, 2015). "The availability of BST-2-deficient mice has allowed the impact of viral infection to be assessed in the absence of endogenous BST-2." (PMID 26566124, 2015).
viral infection (continued). "Viral infection is generally accompanied by the induction of interferon in the blood of infected individuals, which in turn initiates a cascade of feedback loops, known to involve BST2 upregulation." (PMID 23840623, 2013). "Therefore, we determined the amount of the major tegument proteins pp71 and pp65 recovered from BST2-expressing or control THFs immediately after virus infection and prior to onset of immediate early gene expression." (PMID 22072961, 2011). "Our data suggest that feline Tetherin/BST-2 functions as a part of IFN-induced innate immunity against virus infection and that the induction of feline Tetherin/BST-2 in vivo may be effective as a novel antiviral strategy for viral infection." (PMID 21479233, 2011). "Additionally, a neutralization assay using sera from the Bst2+/+ and Bst2−/− DC-vaccinated mice showed significant differences in the ability to block viral infection (84.7% neutralization by the Bst2+/+ DC-vaccinated group vs. 50.5% by the Bst2−/− DC-vaccinated group)." (PMID 39796009, 2024). "Although the immune response of the ocular surface is not completely understood, differences in the respective responses of the cornea and conjunctiva to viral infection could be potentially related to the different expression of BST2 in the epithelia of the two tissues." (PMID 37389178, 2023). "Among those upregulated ISGs, we selected four, BST2, ZBP1, CXCL11, and IFITM1, for future exploration as druggable targets to attenuate viral infection." (PMID 39874350, 2025). "Tetherin, also known as BST-2/CD317/HN1.24, is a GPI-anchored transmembrane protein and restricts virus infection by tethering the viral progeny to the cell surface." (PMID 38392865, 2024). "In this respect, it is also reported that types I and III IFNs are important cytokines to inhibit viral infection by inducing antiviral genes including anti-SARS-CoV-2 genes such as LY6E and BST2." (PMID 36703213, 2023). "It has been reported that interferon can significantly trigger the production of many interferon-induced genes (IFIT1, IFITM3, MX-1, OASL, ISG15, PKR, GBP1, Viperin, BST2, IRF-1, and CXCL10), which play key roles in the resistance to viral infection." (PMID 36337195, 2022). "Several ISGs have been shown to decrease HCV replication by affecting virus infection (Mx, TRIM, IFITM, CH25H), viral RNA translation, replication, stability (OAS, IFIT, GBP1), or virus packaging and release (tetherin/BST2, viperin)." (PMID 32214045, 2020). "To this end, we infected wild type (WT) and BST-2 knockout (KO) mice intravenously (i.v.)with LCMV clone 13 (Cl-13), a strain known to establish a chronic viral infection in immune competent adult mice." (PMID 30028868, 2018). "HM1.24 antigen (also referred to as CD317, BST2, or tetherin) is a surface molecule involved in controlling virus infection." (PMID 22611422, 2012). "Supporting the importance of these genes, a recent study demonstrated that in Caco-2 cells, human colon cancer cells, knockout of BST2 led to increased SARS-CoV-2 dissemination and replication, reinforcing the importance of this gene in restricting viral infection." (PMID 39874350, 2025). "Indeed, in BCi-NS1.1 infected cells, we clearly observed a strong downregulation of BST2 expression by immunofluorescence, whereas the induction of BST2 expression, due to IFN response to viral infection is clearly observed in neighboring uninfected cells." (PMID 39561185, 2024). "BST2 induces NF-κb-dependent proinflammatory gene expression right after viral infection and prevents prolonged IFN production in a negative-feedback manner." (PMID 36176574, 2022). "At the gene level, we found that NF could significantly induce a set of ISG expressions, such as MCL1, IFITM3, B2M, BST2, OAS1, and PKR to function against virus infection." (PMID 35910807, 2022). "We speculate that IFI27, BST2, MX1 and ISG15 may play an important role in the suppression of ZIKV and other viral infections rendered by NS4A." (PMID 35522620, 2022).
viral infection (continued). "Meanwhile, we found that IFNs could significantly trigger the production of a variety of IFN-induced genes (IFIT1, IFITM3, Mx-1, OASL, ISG15, PKR, GBP1, Viperin, BST2, IRF-1, and CXCL10) and MHC molecules, which play key roles in resistance to virus infection." (PMID 32655518, 2020). "Here, we sought insights into whether BST-2 interferes with the release and propagation of the prototypic arenavirus, LCMV, both in cultured cells and during the establishment of a persistent viral infection in mice." (PMID 30028868, 2018). "Furthermore, in future experiments, reintroducing MARCHF8 or NDP52 after knockout may help us quickly determine the role of MARCHF8 or NDP52 in viral infection and may promote the inhibition of SADS-CoV replication by BST2." (PMID 40871369, 2025). "Although BST2 is selectively expressed on mouse pDC in naïve mice, it is also expressed by plasma cells and is upregulated on most cell types, including classical DC, B cells, T cells, myeloid cells, NKT cells and stromal cells following viral infections or stimulation with IFNs." (PMID 24204273, 2013). "Thus, unlike a bona-fide receptor, BST2 is not essential for infection because viral infection also occurs in the absence of BST2, particularly in fibroblasts." (PMID 22072961, 2011). "To examine the role of BST-2 in virus infection in vivo, we first determined whether MMTV target cells and tissues such as dendritic cells (DCs), macrophages (MΦs), lymph nodes and spleens from different mouse strains (C3H/HeN and C57BL/6) that express BST-2 mRNA." (PMID 22284121, 2012).